BRAF (B-Raf proto-oncogene, serine/threonine kinase)
Diseases named in the same sentence as BRAF in open-access papers (continued):
Sharing a sentence is not in itself a finding about the gene and the disease.
melanoma (continued). "The role of BRAF-mutations is underlined by advances in the treatment of melanoma with BRAF inhibitors but the exact role of BRAF in the initiation or progression of melanoma is still unknown." (PMID 23861977, 2013). "Finally, we extended the investigation about the distribution of BRAF-NRAS mutations to a larger series of different melanoma tissues." (PMID 23987572, 2013). "Furthermore, BRAF signaling, activated in most of melanomas through mutation or autocrine/paracrine activation, inhibits Wnt/β-catenin signaling in human melanoma cells and β-catenin is required for PLX4720-induced apoptosis in melanoma cells." (PMID 24416617, 2013). "Mutations in the gene encoding BRAF were first described in malignant melanoma in 2002." (PMID 24455362, 2013). "Compared with dacarbazine, ipilimumab has been shown to improve OS in a randomized trial in patients with previously treated metastatic melanoma, while vemurafenib improved OS and PFS in a randomized trial in patients with previously untreated melanoma harboring the V600 BRAF mutation." (PMID 23402397, 2013). "Melanomas have a high frequency of mutant BRAF mutations, and in papillary thyroid cancer, expression of mutant BRAF is associated with inhibition of MST1/2 kinases; it would be interesting to determine whether this is also the case in melanoma." (PMID 23720711, 2013). "Although MEK inhibitor is known to suppress proliferation of melanoma with either NRAS or BRAF mutation, it remains to be evaluated whether the inhibitor also has immunological effects, such as stimulating or suppressing activity on anti-tumor T cells." (PMID 23755373, 2013). "We next asked whether our approach could be suitable for detection of other mutant BRAF variants within the activation segment in exon 15 in both melanoma and other tumors." (PMID 23555633, 2013). "Melanoma, a malignant tumor derived from melanocytes, causes the majority of deaths attributed to skin cancer, even though recent progress in the design of melanoma-targeted therapies such as the V600E-mutation directed BRAF-inhibitor vemurafenib has been achieved." (PMID 23429201, 2013). "These include gefitinib and erlotinib for non-small-cell lung cancer patients with EGFR mutations, panitumumab and cetuximab for metastatic colon cancer, vemurafenib for patients with melanomas harboring BRAF mutations, and crizotinib for lung cancer patients with EML4-ALK translocations." (PMID 23805382, 2013). "However, studies of other cancers such as melanoma have revealed clearly targetable changes such as activating mutations in BRAF, which have already had a profound impact on clinical care." (PMID 23653877, 2013). "FLOT2 might promote PAR-1-induced constitutive signaling through the BRAF-MAPK-ERK pathway implicated in melanoma progression." (PMID 23945257, 2013). "Over 50% of melanomas, a highly lethal form of skin cancer, carry mutations in a gene called BRAF." (PMID 24192036, 2013). "However, the discovery that 40%–50% of melanomas harbor activating BRAF mutations prompted the development of selective BRAF inhibitors." (PMID 27429258, 2013). "It is not known whether melanocytic nevi that are found in association with a melanoma are more likely to carry BRAF or NRAS mutations than uninvolved nevi." (PMID 23861977, 2013). "In melanoma, approximately 40% of patients have BRAF mutations of which 69% are V600E." (PMID 24066160, 2013). "In particular we used CCRF-CEM cell line as reference for KRAS mutation p.G12D (heterozygous), the human colorectal carcinoma cell line SW620 (used as reference for KRAS mutation pG12V, homozygous), and the human melanoma cell lines A375 (used as the source of homozygous BRAF V600E DNA)." (PMID 23536897, 2013). "Although carried out on a limited series of melanoma cell lines, our study provided evidence that dabrafenib may exert a wider inhibitory activity on oncogenic variants of BRAF." (PMID 23317446, 2013).
melanoma (continued). "In addition, RAS mutations (HRAS, KRAS, or NRAS) have been identified in ∼55–60% of thyroid cancers, and BRAF mutations have been identified in ∼60% of malignant melanomas." (PMID 23991070, 2013). "Moreover, BRAF mutations are associated with a Rac-dependent cadherin switch in melanoma, suggesting a link to the cytoskeleton." (PMID 23720711, 2013). "50%–60% of melanomas contain an activating mutation in BRAF." (PMID 23634303, 2013). "This suggest that PXAs in general do not have the complex genetic background of other BRAF driven tumors, such as melanoma, and may make them particularly susceptible to BRAF inhibition." (PMID 23592488, 2013). "In melanomas, the BRAF mutations are targeted with Vemurafenib." (PMID 23863689, 2013). "The data presented in this study demonstrated that MEK inhibition determines a strong antitumor activity against the more tumorigenic metastatic melanoma cells expanded in vitro as melanospheres and against melanospheres-generated xenografts both with mutated or wild type BRAF." (PMID 24238212, 2013). "Patients with melanoma bearing other BRAFV600 mutations may also respond to BRAF inhibitors or/and MEK inhibitors." (PMID 23976959, 2013). "Some but not all of these cell lines exhibited NRAS mutations, suggesting that some melanomas that are wildtype for both BRAF and NRAS may respond to trametinib, a MEK inhibitor." (PMID 23658559, 2013). "Clinical trials have shown that a drug called vemurafenib can be used to treat patients who carry the mutated BRAF genes and go on to develop melanoma, but around one fifth of these patients developed another type of skin cancer called cSCC (cutaneous squamous cell carcinoma)." (PMID 24192036, 2013). "Overall 65% of melanoma had a BRAF or NRAS mutation in a mutually exclusive pattern." (PMID 23694694, 2013). "In addition to the patient subsets described previously for the phase III trials, ipilimumab has demonstrated activity in patients with melanoma brain metastases and in melanoma patients with mutations in the BRAF kinase." (PMID 23772560, 2013). "Notably, one specific mutation, p.V600E/c.1799T>A, accounts for around 90% of BRAF mutations found in melanoma." (PMID 23603840, 2013). "Thus, since June 2011the determination of BRAF mutational status has been obligatory, to determine the best treatment options for patients with late-stage melanomas." (PMID 24119386, 2013). "Activating mutations in BRAF (mainly V600E/K) have been identified in half of all melanoma cases, and the development of novel compounds targeting mutated BRAF, or compounds boosting the immunological responses directed towards cancer cells, has given new hope to this group of patients." (PMID 24023633, 2013). "Therefore, our findings in the pooled data suggest that with successful BRAF inhibition we would be able to increase the survival of colorectal cancer and melanoma patients harboring BRAF mutation." (PMID 23056577, 2012). "Genome-wide array CGH approaches have been used to discriminate between nevi and melanoma, and specific genomic alterations were found to be associated with histological subtypes of melanoma, BRAF mutations, anatomical site as well as pattern of UV radiation exposure." (PMID 22535842, 2012). "Often melanoma cells with BRAF mutations also contain PTEN or PIK3CA mutations." (PMID 23085539, 2012). "The rapid transition from scientific findings to clinical application is exemplified by both the finding of BRAF mutations in melanoma in 2002 and FDA approval of vemurafenib for this indication in 2011 and that of the initial finding of EML4-ALK in 2007 and FDA approval of crizotinib in 2011." (PMID 25562798, 2012). "V600E BRAF is a frequent mutation in melanoma and is also commonly found in benign nevi." (PMID 22216021, 2012). "Specifically NRAS and BRAF mutations are highly associated with melanoma." (PMID 22216021, 2012). "This suggests clonal heterogeneity in terms of BRAF mutations during melanoma progression." (PMID 22281663, 2012).
melanoma (continued). "This approach could be particularly promising in malignant melanomas harboring the BRAF mutation, taking into account the role played by the interaction of those kinases in the malignant transformation." (PMID 22216021, 2012). "BRAF V600E has been implicated in papillary thyroid carcinoma, colorectal carcinoma, and melanoma." (PMID 22745804, 2012). "Among the first 150 melanomas genotyped with informed consent (from 07/08/2010 to 12/13/2010), 90 (60%) had at least one mutation, including 57, 23, 6, 3, and 2 mutations in BRAF, NRAS, GNAQ, KIT, and CTTNB1, respectively." (PMID 22536370, 2012). "For disseminated disease palliative chemotherapy regimens have included use of chemotherapy and immunotherapy agents such as dacarbazine (DTIC), ipilimumab (IPI), interferon-α, aldesleukin, and BRAF inhibitors such as vemurafenib (in patients with BRAF-mutated melanoma)." (PMID 23133758, 2012). "In current neuropathological practice, BRAF testing can be of clinical value in tissue samples of melanoma brain metastases from patients with unknown mutation status in order to identify cases amenable to therapy with BRAF inhibitors." (PMID 22385786, 2012). "The aim of the current study was to utilize a diverse melanoma cell line panel (n = 31) of known mutational status (BRAF, HRAS, NRAS, and phosphatase and tensin homolog (PTEN)) to aid in the identification of a patient population most likely to respond to MEK inhibition." (PMID 23039341, 2012). "Indeed, there are 21 clinical trials listed on the Clinical.Trials.gov website with MEK inhibitors and melanoma patients which often have mutation of BRAF and hence activation of downstream MEK." (PMID 23085539, 2012). "It is now known, however, that sorafenib is inactive in patients with BRAF-mutated melanoma, and the role of combination therapy with the newer selective BRAF inhibitors in patients whose tumors carry the BRAFV600E mutation is unknown." (PMID 23228035, 2012). "The melanoma models used in our study were derived from both primary and metastatic sites (including skin, lymph node, and brain) of both nodular and superficial spreading melanomas and almost generally harbored mutations in either BRAF or NRAS genes." (PMID 22535842, 2012). "Furthermore, novel BRAF inhibitor molecules like vemurafenib are proving highly effective to treat patients with BRAF mutated tumors, like melanoma." (PMID 22558339, 2012). "Similarly in melanoma, 50% of cases have BRAF mutations in exon 15 mostly V600E and these cases are sensitive to the BRAF inhibitors vemurafenib or dabrafenib." (PMID 25562798, 2012). "Thus, in this in-vitro model experiment, the BRAF mutation was successfully detected in individual melanoma cells isolated from peripheral blood." (PMID 22281663, 2012). "While sorafenib is not considered effective for the treatment of most melanomas with BRAF V600E mutations, it may be effective in the treatment of a minority of melanomas with G469E and D594G mutations which express constitutive ERK1/2 but low levels of MEK." (PMID 23085539, 2012). "About 50 % of melanomas harbors activating BRAF mutations (over 90 % V600E)." (PMID 22554099, 2012). "Hence, in melanomas in which BRAF or NRAS mutations are present, they would be expected to be responsive to therapeutic interventions targeting the RAS-RAF-ERK and PI3K pathways, such as sorafenib." (PMID 22110486, 2012). "It was interesting that eleven of the molecules previously implicated in melanoma pathogenesis (described in the introduction) were identified as hubs in the Bayesian gene networks generated from our A375 cell dataset, including: BRAF, CCND1, RB1, PTEN, TYR, CDKN2A, and SOX10." (PMID 22536322, 2012). "In addition to the BRAF mutations present in melanomas that we have previously discussed, the PTEN phosphatase tumor suppressor gene is also deleted in approximately 45% of melanomas and the downstream AKT gene is amplified in approximately 45%." (PMID 23085539, 2012).
melanoma (continued). "However, evidence for constitutive phosphor-JNK expression was also found in human melanoma lines expressing BRAF or NRAS activating mutations." (PMID 23173060, 2012). "At least 6 genes have been shown to be recurrently mutated in melanoma, including the serine-threonine kinase encoded by BRAF; the receptor tyrosine kinase encoded by KIT; the GTP-binding proteins encoded by NRAS, GNA11, and GNAQ; and the WNT signaling pathway component encoded by CTNNB1." (PMID 22536370, 2012). "This variation in the detection of the BRAF mutation within single tumor samples supports the hypothesis that melanomas are comprised of tumor subclones that differ with respect to the mutational status of the BRAF gene." (PMID 22235286, 2012). "It has marked antitumor effects against melanoma cell lines with the BRAF V600E mutation only." (PMID 22333219, 2012). "BRAF mutation is commonly present in cancers, especially melanoma and colon cancers." (PMID 22792460, 2012). "In addition, we revealed that BRAF-V600E mutation also increases the risk of mortality in melanoma patients by 1.7 times, while its effect on papillary thyroid carcinoma still requires further investigation." (PMID 23056577, 2012). "In a study of Raf265-resistant melanomas containing the BRAF V600E mutation, it was observed that protein kinase D3 (PRKD3) mediated resistance to both Raf and MEK inhibitors and siRNA knockdown of PRKD3 cooperated with Raf265 in suppressing the growth of the resistant melanoma cells." (PMID 23085539, 2012). "In addition, we revealed that BRAF-V600E mutation also significantly increases the risk of mortality in melanoma patients." (PMID 23056577, 2012). "Among the 57 melanomas with BRAF V600 mutations, 35 originated from intermittent sun damaged skin, 10 from chronic sun damaged skin, 2 from acral sites, 2 from mucosal sites, and 8 from unknown primary sites." (PMID 22536370, 2012). "In addition, we revealed that BRAF mutation also increases the risk of mortality in melanoma patients by 1.7 times (95% CI, 1.37–2.12)." (PMID 23056577, 2012). "Thus, most primary melanoma lesions so far examined consist of melanoma cells that contained wild-type BRAF admixed with melanoma cells that contained V600E and other BRAF mutations." (PMID 21224857, 2011). "This suggests that BRAF mutation may actually be an acquired event in early melanoma that leads to clonal expansion and tumor progression." (PMID 22175026, 2011). "Clinical detection of oncogenic point mutations conferring enzymatic gain-of-function has been a fruitful strategy for triaging patients to molecularly targeted therapy in several cancer types, including lung adenocarcinoma (EGFR mutations) and melanoma (BRAF V600E mutations)." (PMID 22194861, 2011). "Furthermore, two primary melanomas (cases 1 and 3) also contained tumour cells with other BRAF mutations, such as K601R, V600M and V600-K601E, all of which have been reported in melanoma." (PMID 21224857, 2011). "However, several studies have shown that BRAF mutations are very uncommon in melanomas arising in sun-protected areas." (PMID 21827678, 2011). "Due to the detection of the V600E BRAF mutation in this fistula melanoma, it was decided not to look for alterations in genes such as CCND1 or KIT, more frequently mutated in acral and mucosal melanomas, since concomitant mutations in BRAF and in genes such as KIT or CCND1 are extremely rare." (PMID 21827678, 2011). "To examine whether BRAF mutant alleles are selected for in melanoma progression, we enumerated BRAF mutant alleles by subcloning in three cases where the pairs of primary tumour and recurrent primary tumour or metastases were available for analyses." (PMID 21224857, 2011).
melanoma (continued). "With the advent of improved methods of DNA sequencing, it was demonstrated that BRAF is frequently mutated in melanoma (27 to 70%), papillary thyroid cancer (36 to 53%), colorectal cancer (5 to 22%), cholangiocarcinoma (22%), ovarian cancer (30%), and a small minority of lung cancer patients (1-3%)." (PMID 21422497, 2011). "However, this is unlikely because the minor population of melanoma cells with BRAF mutations became predominant in a recurrent primary tumour or metastases that developed in the same patients." (PMID 21224857, 2011). "However, recent studies have also shown that the frequency of mutation of the BRAF gene in melanomas has clear discrepancies depending on the subtype of melanomas." (PMID 21911917, 2011). "A primary melanoma cell line MMG1 also showed BRAF mutation heterogeneity." (PMID 21224857, 2011). "This BRAF mutation accounts for > 90% of the BRAF mutations found in melanoma and thyroid cancer." (PMID 21422497, 2011). "Mutations in NRAS and BRAF are present in ∼20% and >50% of melanomas, respectively." (PMID 21750549, 2011). "While it is clear that CRAF activation and enhanced MAPK pathway signaling occur in BRAFWT melanoma cells (particularly those which harbor an NRAS mutation) treated with BRAF inhibitors such as vemurafenib and PLX4720, the clinical relevance of this is uncertain." (PMID 22175026, 2011). "Similarly, BRAF mutations affecting codon 600 constitute >90% of melanoma BRAF mutations; genetic changes in an additional 10–12 codons account for most of the remaining cancer-associated BRAF mutations identified to date." (PMID 21931712, 2011). "Our study showed that cytoplasmic Skp2 expression was increased in melanoma, which may be due to BRAF mutation." (PMID 21386910, 2011). "Tumour heterogeneity in terms of BRAF mutations was also shown in 8 of 10 primary melanomas." (PMID 21224857, 2011). "In this study, we have tested whether a similar heterogeneity of BRAF mutations exists in primary melanomas." (PMID 21224857, 2011). "In some melanomas, BRAF mutations occur along with other mutations in genes such as PTEN and CDK4." (PMID 21479172, 2011). "We next asked whether BRAF-V600E-mutated melanoma cells escaped from PLX4720 therapy and become drug resistant." (PMID 20531415, 2010). "Activating mutations in BRAF kinase are common in melanomas." (PMID 20630094, 2010). "The discovery that ∼50% of human melanomas harbour activating V600E mutations in the serine/threonine kinase BRAF has raised the possibility that these tumours may be amenable to targeted therapy." (PMID 20531415, 2010). "Activating mutations in BRAF occur in ~7% of all human cancers including melanoma, papillary thyroid and colon cancer; the V600E mutation is the most common mutation occurring in approximately 70% of melanoma patients." (PMID 21301046, 2010). "Interestingly, as the melanoma DNA yield decreased, there was little drop-off in the percentage of BRAF or NRAS mutations detected using either ARMS or sequencing." (PMID 20925915, 2010). "Combined BRAF/MEK inhibition may be one strategy to prevent the emergence of drug resistance in BRAF-V600E-mutated melanomas." (PMID 20531415, 2010). "Early clinical studies revealed evidence of Hsp90 target modulation and some signs of biological activity (stable disease) in melanoma patients that may potentially be associated with the presence of BRAF or NRAS mutation." (PMID 21037799, 2010). "V600E BRAF is the most common kinase mutation in melanoma (60%)." (PMID 24281101, 2010). "BRAF mutations found in the melanoma samples using a combination of DNA sequencing and ARMS." (PMID 20925915, 2010). "If a responsive subset of BRAF-mutated melanomas can be identified, it may be possible to rapidly develop RAF and MEK inhibitors as single agents for this population, whereas combination strategies are explored for the remaining." (PMID 19156138, 2009). "More recently, BRAF mutations have been detected in cfDNA of patients with melanoma." (PMID 19861964, 2009).